RN7SKP105 (RN7SK pseudogene 105)
Gene: Miscellaneous RNA gene on chromosome 4 (163,828,800 to 163,829,113, reverse strand). Ensembl gene ENSG00000253001.
Homologues: Orthologues: chimpanzee 7SK (98% identical), mouse Gm55389 (41% identical), mouse Gm54881 (40% identical). Paralogues in human: RN7SKP77 (59% identical), RN7SKP85 (59% identical), RN7SKP245 (58% identical), RN7SKP217 (57% identical), RN7SKP124 (57% identical), RN7SKP161 (57% identical), RN7SKP185 (57% identical), RN7SKP30 (57% identical), RN7SKP249 (56% identical), RN7SKP79 (56% identical), RN7SKP33 (56% identical), RN7SKP97 (56% identical), and 284 more.